HSD3B1 (hydroxy-delta-5-steroid dehydrogenase, 3 beta- and steroid delta-isomerase 1)
Diseases named in the same sentence as HSD3B1 in open-access papers (continued):
Sharing a sentence is not in itself a finding about the gene and the disease.
hepatocellular carcinoma (1 paper, 2022). A malignant tumor that arises from hepatocytes. "Within hepatocellular carcinoma (HCC), studies in vitro have recently shown that inhibition of HSD3B1 with trilostane caused significant inhibition HCC cell clonogenicity and cellular migration." (PMID 37435458, 2022).
hyperuricemia (1 paper, 2023). An abnormally high level of uric acid. "Compared with the control mice, the mRNA levels of enzymes such as cytochrome P450 family 11 Subfamily a member 1 (CYP11A1), 11β-hydroxylase (CYP11B1), aldosterone synthase (CYP11B2) and 3β-hydroxysteroid dehydrogenase 1 (HSD3B1) were significantly lower in the adrenal of hyperuricemia mice." (PMID 38034015, 2023).
major depression (1 paper, 2021). "HSD3B1 is related to the ADHD pathogenesis in rat and a top GWAS hit for major depression." (PMID 33671795, 2021).
metastatic cancer (1 paper, 2021). A carcinoma which has spread from the original site of growth to another anatomic site. "Recently, HSD3B1 (1245C) was also shown to be associated with a higher overall mortality in low-volume metastatic cancer." (PMID 33921650, 2021). "This may be explained by the fact that, compared to those with metastatic cancer, most individuals with localized PC survive longer after diagnosis and die not from PC, and other factors may have a stronger impact on their mortality than HSD3B1 (1245C)." (PMID 33921650, 2021).
myopia (1 paper, 2011). "We observed associations between certain combinations of polymorphisms at steroidogenesis enzyme genes (rs6203 [HSD3B1], rs10046 [CYP19A1], and sex) and high-myopia risk; meanwhile, there is evidence of correlations between rs605059 (HSD17B1)–sex interaction and sex hormone levels." (PMID 21921981, 2011). "An MDR analysis corroborated the synergistic genotype association and demonstrated that synergistic interaction between rs6203 (HSD3B1), rs10046 (CYP19A1), and sex might confer susceptibility to high myopia (p=0.019)." (PMID 21921981, 2011).
polycystic ovary syndrome (1 paper, 2016). A disorder that manifests as multiple cysts on the ovaries. "Furthermore, the expression levels or enzymatic activities of CYP17A1 and HSD3B1 have been related to androgen production in polycystic ovary syndrome." (PMID 27057163, 2016).
varicocele (1 paper, 2012). A condition characterized by the dilated tortuous veins of the spermatic cord with a marked left-sided predominance. "For example, in the mouse testis, HIF-1α regulates the expression of the 3β-hydroxysteroid dehydrogenase type I (Hsd3b1) gene in Leydig cells, and up-regulated expression of HIF-1α has been reported in experimentally-induced varicoceles in the rat testis." (PMID 23216940, 2012).
tumor (24 papers, 2013 to 2025). "Our study instead depicts an association of the HSD3B1 variant status as a potential regulator of the tumor microenvironment." (PMID 40282446, 2025). "Results highlight context-specific associations between germline HSD3B1 genotypes and tumor biology in BC and EC." (PMID 40565184, 2025). "In this study, we classified samples based on the HSD3B1 genotype as either adrenal-permissive or -restrictive, using our recently developed approach to infer germline HSD3B1 status using the variant allele frequency (VAF) obtained from tumor DNA sequencing." (PMID 40565184, 2025). "As we examined tumor sites within the 22 adrenal metastasis samples, it was clear that HSD3B1 and CYP3A43 exhibited robust association with AR expression (R = 0.7 and 0.56), whereas the rest of the APUC-6 genes did not." (PMID 39207857, 2024). "Upon examine RNA-sequencing profiles, samples harboring the adrenal-permissive HSD3B1 were associated with overexpression of genes belonging to ten pathways representing increases of cell-cycle and tumor proliferation." (PMID 37435458, 2022). "An ongoing clinical trial (NCT05183828) is evaluating whether the HSD3B1 germline variant influences tumor proliferation markers, hormone receptor expression, and letrozole response in postmenopausal women with ER + HER2- BC." (PMID 40565184, 2025). "Altogether, while the observations in PC indicate that variant status of HSD3B1 has limited impact on the tumor-intrinsic genome, HSD3B1 variant status may impact the tumor genome in other cancers and different clinical settings." (PMID 40282446, 2025). "In TNBC and EC, where hormonal dependence is variable, the absence of genotype-associated survival differences may similarly reflect tumor heterogeneity or the limited role of HSD3B1 in late-stage disease." (PMID 40565184, 2025). "We analyzed BC and EC sequenced from patients that received diagnostic tests in oncology clinics, and we determined the germline HSD3B1 c.1100 genotype (AA, AC, CC) from tumor DNA sequencing by using variant allele frequency, with inferred menopausal status assumed by age at molecular profiling." (PMID 40565184, 2025). "APUC genes, such as the HSD3B1 genetic variants, may also interact with other tumor-promoting pathways such as the cell cycle." (PMID 37435458, 2022). "This study is the first to highlight racial disparities in the HSD3B1 genotype distribution across all tumor subtypes." (PMID 40565184, 2025). "To investigate the potential tumor-intrinsic effects of the HSD3B1 genotype, we performed differential gene expression analyses comparing BC and EC tumor subtypes that harbor either the CC or AA genotypes." (PMID 40565184, 2025). "Our study demonstrates that HSD3B1 genotypes distinctly impact tumor transcriptional profiles, genomic alterations, and the expression of immune and non-immune pathways across BC and EC subtypes, in both pre- and postmenopausal tumors." (PMID 40565184, 2025). "As a germline biomarker, HSD3B1 circumvents the caveats of detecting somatic alterations, which include tumor DNA fraction, tumor heterogeneity, or the potential necessity of invasive tumor biopsies." (PMID 39286977, 2024). "However, other tumor-level alterations in HSD3B1 are known to occur, including somatic mutations, phosphorylation of the 3βHSD1 protein, regulation by cancer-associated fibroblasts, and regulation by hypoxia-dependent mechanisms, which may contribute to clinical outcomes." (PMID 39286977, 2024). "Specifically, higher O-GlcNAcylation in tumor cells treated with glucosamine induced Elk1-mediated transcription of HSD3B1 and increased tumor cell viability." (PMID 37009898, 2023). "Here, we demonstrate that CAFs in the tumor microenvironment can increase HSD3B1 transcription to promote CRPC progression." (PMID 37009898, 2023). "The results showed that, except for HSD3B1, 16 lncRNAs and mRNAs were significantly differentially expressed in normal and tumour tissues." (PMID 35454778, 2022).
tumor (continued). "Mechanistically, HER2‐IL6 signalling axis enhances the expression of androgen biosynthetic enzyme HSD3B1 and increases SRB1‐mediated cholesterol uptake in SPRY2‐deficient tumours." (PMID 29540470, 2018). "Mechanistically, loss of the tumour suppressor SPRY2 leads to activation of the HER2‐IL6 cytokine signalling axis, which enhances tumoral expression of androgen biosynthetic enzyme HSD3B1 and lipoprotein receptor SRB1." (PMID 29540470, 2018). "Overall, these racial differences in the HSD3B1 genotype distribution may have important clinical implications, where 3βHSD1-mediated adrenal androgen metabolism could influence tumor biology, disease progression, and treatment outcomes." (PMID 40565184, 2025). "Given the limited influence on genomic alterations, we hypothesized that differences between the c.1100 AA and CC HSD3B1 genotypes could be detected in the tumor transcriptomes." (PMID 40282446, 2025). "Altogether, it is worth noting that HSD3B1 genotypes, regulated by local tissue type, may impact the tumor microenvironment, and that this process is also regulated by local tissue type." (PMID 40282446, 2025). "Altogether, these differences indicate that the HSD3B1 c.1100 genotypes, albeit exhibiting limited change in individual genes, had a significant impact on signaling pathways and immune regulatory pathways in a tumor-site-specific manner." (PMID 40282446, 2025). "Our hypothesis is that HSD3B1 genotypes could correlate with distinct tumor characteristics and clinical outcomes in pre- and postmenopausal BC and EC subtypes." (PMID 40565184, 2025). "The overexpression of HSD3B1 could result in the increased production of androstenedione, which in turn elevates the estrogen hormone levels of the tumor cell." (PMID 37415453, 2023). "Mechanistically, the adrenal-permissive HSD3B1 allelic status may regulate either the tumor or be conditioning its microenvironment and in turn supporting resistance to ADT and subsequently developing worse survival outcomes at increased rates." (PMID 37435458, 2022). "We have presented evidence in which other less studied APUC genes may have similar functions as HSD3B1 both in a population and in tumor cells." (PMID 37435458, 2022). "The ADT‐resistant NPS tumours also showed elevated levels of HSD3B1 (Fig EV3F)." (PMID 29540470, 2018). "Whether D4A, a pan inhibitor of androgen biosynthetic enzymes, sensitised CRPC with high HSD3B1 expression (e.g., SPRY2‐deficient CRPC tumours) to ADT requires further investigation." (PMID 29540470, 2018). "Altogether, while tumor-intrinsic features are not regulated by germline HSD3B1 c.1100 alleles, these genotypes instead may impact cell–cell interactions and the tumor microenvironment." (PMID 40282446, 2025). "While these findings support a role for germline HSD3B1 at the population level, the functional consequences of germline HSD3B1 genotypes in human tumors remain largely uncharacterized in the literature, with limited mechanistic insights into tumor-specific effects." (PMID 40565184, 2025). "Interestingly, expression of several estrogen synthesis genes (CYP17A, CYP19, HSD17B1, CYP21 and HSD3B1) was detected more frequently in tumor tissue than in normal tissue, with CYP19 (aromatase) and HSD3B1 only detected in tumors." (PMID 29290988, 2017). "Recent clinical observations have revealed predominant expression of HSD3B2 mRNA and protein in tumor cells of aldosterone-producing adenoma (APA), and HSD3B1 mRNA significantly correlated with CYP11B2 mRNA levels and plasma aldosterone concentrations in APA patients." (PMID 27057163, 2016).
cancer (16 papers, 2017 to 2025). A tumor composed of atypical neoplastic, often pleomorphic cells that invade other tissues. "HSD3B1 and its variants have previously been implicated in multiple forms of cancer." (PMID 40282446, 2025). "As of now, our findings support the potential of germline HSD3B1 genotype as a clinically relevant genetic marker that could be incorporated into the existing diagnostic workflows for these endocrine-driven cancers." (PMID 40565184, 2025). "Overall, transcriptional variation dependent on HSD3B1 genotypes differed by the cancer type, with the majority of differences seen in TNBC and less variation observed in ER + BC and endometrioid EC." (PMID 40565184, 2025). "Contrary to early reports, we did not observe statistically significant differences in OS based on the HSD3B1 genotype in any cancer subtype or menopausal group." (PMID 40565184, 2025). "In ER + BC, significant differences in genomic alterations were observed across HSD3B1 homozygous genotypes in each of the cancer subtypes." (PMID 40565184, 2025). "We observed notable differences in the HSD3B1 genotype distribution when stratified by the cancer subtype and inferred menopausal status." (PMID 40565184, 2025). "CAF production of glucosamine increases GlcNAcylation in cancer cells, promoting Elk1-induced HSD3B1 transcription." (PMID 37009898, 2023). "Although the expression level of HSD3B1 in cancer tissues was higher than that in normal tissues, the difference was not statistically significant." (PMID 35454778, 2022). "In neuronal cells, the cancer-related gene SLIT2 was found to be upregulated, as were six other cancer-related genes (PDGFRA, DDR2, RSPO3, IL6ST, NTRK2, and HEY1) in cardiomyocytes and one cancer-related gene (HSD3B1) in hepatocyte-like cells." (PMID 32127560, 2020). "However, as the diagnostic testing of tumors is biased toward late-stage disease, the role of HSD3B1 in the early stages of cancer remains to be determined in human tumors." (PMID 40565184, 2025). "IL4 induction of HSD3B1 expression has been reported in several cancer cell lines." (PMID 36362361, 2022). "Interleukin 4 (IL4) induces the expression of HSD3B1 in various human cancer cell lines." (PMID 36362361, 2022). "Altogether, HSD3B1, HSD3B2, CYP11A1, CYP11B1, CYP17A1, and CYP3A43, hereby defined as APUC-6, demonstrated tissue- and cancer stage–specific interactions, with the most notable interaction in metastatic PC." (PMID 39207857, 2024). "In combination with BLM for cancer, abnormal expression of STAR, CYP11A1, and HSD3B1 led to hormone secretion disorder." (PMID 38137018, 2023). "Regardless, these cross-cancer differences accentuate the need for a more expansive examination with regard to the clinical relevance of HSD3B1, in not just BC and EC, but likely in other cancer types as well." (PMID 40565184, 2025). "Similarly, CAF-CM treatment increased cancer cell viability after DHEA treatment, and HSD3B1 siRNA impeded this effect." (PMID 37009898, 2023).
infection (1 paper, 2019). The state of being infected such as from the introduction of a foreign agent such as serum, vaccine, antigenic substance or organism. "Except for Hsd3b1, infection with S. haematobium did not have an influence on Vitamin D pathway associated (VDR, Cyp27b1) or immunological (IL10, IFNG, Foxp3) genes as well as vitamin D plasma levels." (PMID 31673046, 2019).
prostate (1 paper, 2022). "Similarly to SMARCD1, we found that numerous downstream targets of SMARCD2 (e.g., PTGR1, TRMP8, PGC) and SMARCD3 (e.g., EGF, PIK3AP1, HSD3B1) were AR-driven genes that are involved in prostate tumorigenesis, progression and metastasis." (PMID 36611918, 2022).
HSD3B1 also shares sentences with these, for which no sentence is quoted: colorectal cancer (1 paper); cryptorchidism (1); genetic diseases (1); Gynecomastia (1); hyperaldosteronism (1); Infertility (1); invasive breast carcinoma (1); orchitis (1); ovarian tumor (1).